LINC01301 (long independently transcribed non-coding RNA 1301)
Gene: Long non-coding RNA gene on chromosome 8 (60,284,903 to 60,516,853, reverse strand). Ensembl gene ENSG00000251396.
Diseases named in the same sentence as LINC01301 in open-access papers:
LINC01301 is named in the same sentence as 1 disease in open-access papers, as found by Europe PMC text mining. Sharing a sentence is not in itself a finding about the gene and the disease. The quoted sentences say what the papers report.
COVID-19 (1 paper, 2025). A disease caused by infection with severe acute respiratory syndrome coronavirus 2. "The risk locus rs2875968 spans three genes (RAB2A, LINC01301, and CA8), none of which have strong prior evidence implicating them in COVID-19 physiopathology." (PMID 40208878, 2025).